LYSMD3 (LysM domain containing 3)
Description:
Essential for Golgi structural integrity.
Synonyms: FLJ13542
Tractability: Antibody: UniProt places it where antibodies can reach, with high confidence; its Gene Ontology location is reachable by antibodies, with high confidence; UniProt predicts a signal peptide or a membrane-spanning region. PROTAC: ubiquitination databases record sites on it; its protein half-life has been measured.
Gene: Protein-coding gene on chromosome 5 (90,515,611 to 90,529,596, reverse strand). Ensembl gene ENSG00000176018.
Subcellular location: Cell membrane; Golgi apparatus
Subcellular location (Human Protein Atlas): Cytosol
Gene Ontology:
Molecular function: peptidoglycan binding
Biological process: Golgi organization
Cellular component: Golgi apparatus; Golgi membrane; plasma membrane
Genetic constraint (gnomAD): Loss-of-function variants: 14 observed, 27.78 expected, observed/expected ratio (o/e) 0.5, 90% interval 0.33 to 0.79. The upper end of that interval is the gene's LOEUF score, 0.79, which puts it in group 3 of 6, group 1 being the genes least tolerant of losing a copy. Missense variants: 314 observed, 364.69 expected, observed/expected ratio (o/e) 0.86, 90% interval 0.78 to 0.94. Synonymous variants: 102 observed, 120.79 expected, observed/expected ratio (o/e) 0.84, 90% interval 0.72 to 1.
Homologues: Orthologues: chimpanzee LYSMD3 (99% identical), macaque LYSMD3 (97% identical), dog LYSMD3 (91% identical), pig LYSMD3 (90% identical), rabbit LYSMD3 (87% identical), guinea pig LYSMD3 (86% identical), mouse Lysmd3 (80% identical), rat Lysmd3 (79% identical), zebrafish lysmd3 (47% identical), tropical clawed frog lysmd3 (46% identical), Drosophila melanogaster CG17985 (19% identical), Caenorhabditis elegans lmd-1 (18% identical). Paralogues in human: LYSMD4 (28% identical), LYSMD2 (15% identical), LYSMD1 (14% identical).
Diseases named in the same sentence as LYSMD3 in open-access papers:
LYSMD3 is named in the same sentence as 5 diseases in open-access papers, as found by Europe PMC text mining. Sharing a sentence is not in itself a finding about the gene and the disease. The quoted sentences say what the papers report.
Hypertension (1 paper, 2025). The presence of chronic increased pressure in the systemic arterial system. "Although there is currently no research reporting the association of the genes P2RY10, GPR171, KLC3, and LYSMD3 with hypertension, these genes may indirectly affect the occurrence of hypertension." (PMID 39854379, 2025).
thyroid cancer (1 paper, 2022). "In unpaired samples, the expression levels of COL5A1 and LOXL1 were significantly higher in thyroid cancer than in normal tissues (505 cancer and 59 normal samples), and LYSMD3 levels were significantly lower in thyroid cancer." (PMID 35152572, 2022). "Five survival‐related genes, TMEM63C, COL5A1, LOXL1, ADAMTS2, and LYSMD3 were identified; the expression of COL5A1 and LOXL1 was upregulated in PTC tissues and may be related to OS and PFS of thyroid cancer patients." (PMID 35152572, 2022).
cancer (3 papers, 2022 to 2025). A tumor composed of atypical neoplastic, often pleomorphic cells that invade other tissues. "Among these upregulated genes, Dennd4a, Nfil3, Hspa1b, Chac1, Ddit4, Mex3b, Lysmd3, and Zbtb10 are mainly involved in oxidative stress and inflammation response, whereas Plcxd2, Dusp1, Cep85l, and Dusp8 are generally considered as tumor‐suppressor genes by inhibiting proliferation of cancer cells." (PMID 40231790, 2025). "In support of this model, we find that CETN3, MBLAC2, and LYSMD3, core members of the POLR3G promoter hub, feature particularly high correlation z-scores across cancers." (PMID 37894362, 2023).
tumor (2 papers, 2022 to 2025). "COL5A1, LOXL1, and TMEM63C expression levels were significantly higher and LYSMD3 expression levels were significantly lower in tumor tissues than in the paired normal tissues." (PMID 35152572, 2022).
LYSMD3 also shares sentences with these, for which no sentence is quoted: dyslipidemia (1 paper).